IL13 (interleukin 13)
Diseases named in the same sentence as IL13 in open-access papers (continued):
Sharing a sentence is not in itself a finding about the gene and the disease.
allergic asthma (continued). "Previous studies provide evidence that AD and allergic asthma might share related drivers -i.e., IL-4 and IL-13- and that both conditions may benefit from a common therapeutic inhibition of these Th2 cytokines with dupilumab." (PMID 36035412, 2022). "In allergic asthma, downregulation of ACE2 has been associated with a type 2 immune profile, through which increased levels of IL-13 might reduce the expression of disintegrin and metalloprotease 17 (ADAM-17)." (PMID 35920529, 2022). "Among Th2 cytokines, IL‐5 and IL‐13 have multiple functions in the development of allergic asthma." (PMID 35344296, 2022). "The data from our study exhibited that naringenin can effectively improve allergic asthma by reducing the levels of IL-4 and IL-13 in the lung tissue and reducing the count of eosinophils in BALF, which indicates the anti-inflammatory properties of this phytochemical on the pulmonary system." (PMID 35419072, 2022). "ClusterB was highly linked to the Th2 immune response and had higher expression levels of TSLP, IL-33, IL-4, IL-5, and IL-13, which indicated that clusterB may be related to allergic asthma." (PMID 33763115, 2021). "Furthermore, because allergic asthma is considered a Th2‐type disease, Th2 cytokines such as IL‐4 and IL‐13 are widely applied in vitro to mimic the asthmatic environment." (PMID 33960626, 2021). "We extracted total RNA from the lung tissue of mice from both the control and the F2-administered groups in the allergic asthma model and examined the changes in the Th2 cytokines IL-4, IL-5, and IL-13, eosinophil-recruiting chemokine CCL11 and allergic asthma-related cytokine IL-33 using RT-qPCR." (PMID 34576124, 2021). "In particular, IL-13 and its upstream and downstream signaling pathways have been demonstrated to be essential both for resistance to parasites and for full expression of the allergic asthma phenotype." (PMID 34899381, 2021). "Lebrikizumab is a humanized monoclonal antibody against interleukin-13 (IL-13) which has been used in trials studying the treatment of allergic asthma, atopic dermatitis, and idiopathic pulmonary fibrosis (IPF) by inhibiting the IL-13 driven Th2 inflammatory response." (PMID 34252346, 2021). "Therefore, the higher secretion of IL-4, IL-5, and IL-13 contributes substantially to inflammation in allergic asthma." (PMID 32617136, 2020). "A previous study indicated that FMT 10 mg/kg administrated by intraperitoneal injection could significantly alleviate AHR and decrease Th2 cytokines (IL-4, IL-5, and IL-13) levels in the HDM-induced inflammation of allergic asthma." (PMID 33013383, 2020). "The pathogenesis of allergic asthma involves Th2-type cytokines, such as IL-4, IL-5, and IL-13." (PMID 32915886, 2020). "To explore how TLR2 agonist and miR146a-mimic attenuate OVA-induced allergic asthma, we considered Th1 cytokines, including IgE, IL-4, IL-5 and IL-13, might be involved." (PMID 32600285, 2020). "IL-13 is a pro-inflammatory cytokine involved in allergic asthma." (PMID 32849611, 2020). "Overall, the results of immune profile analysis showed that PGT treatment reduced the populations of IL-5 and IL-13 producing immune cells, such as CD4+ T cells and ILCs, as well as the total amount of IL-5 and IL-13 producing cells in OVA-induced allergic asthma." (PMID 33374657, 2020). "Although the precise molecular mechanisms by which IL-13 modulates this family of miRNAs is unclear, it is tempting to speculate that this represents an opening for therapeutically intervention in allergic asthma." (PMID 32155783, 2020). "In addition to IL-4, IL-13 also contributes in the progression of allergic asthma by promoting mucus hypersecretion and eosinophils accumulation." (PMID 32617136, 2020). "Treatment of mice with experimental allergic asthma with human recombinant tumstatin let to a significant reduction of hallmark disease features (e.g., airway hyperresponsiveness, ma-VEGF, eosinophil influx, IL13)." (PMID 32411147, 2020).
allergic asthma (continued). "The direct implication of epithelial miR-375-3p in allergic asthma is unknown, as well as the exact mechanism of action by which IL-13 modulates miR-375-3p, and miR-375-3p relevant targets in the lung." (PMID 32155783, 2020). "Given the established role of IL-13 in promoting goblet cell hyperplasia, lung inflammation and AHR in allergic asthma, our studies reveal a unique role for CD2 in the regulation of Th2-associated allergic asthma." (PMID 32477356, 2020). "In particular, IL-13 plays a pivotal role in allergic asthma." (PMID 31262043, 2019). "Moreover, IL-13 is one of the two crucial cytokines in the isotype switch of B cells towards IgE in allergic asthma." (PMID 31395084, 2019). "Thus, our data suggest that NIP45 not only plays a crucial role in the differentiation of Th2 cells but also in the differentiation of ILC2s in allergic asthma, because it is able to induce IL-4 as well as IL-13." (PMID 31666531, 2019). "Augmented expression of IL-13 in airways of METS-exposed murine offspring correspond with demethylation at the IL13 promoter demonstrating alterations to DNA methylation induced by METS exposure contribute to pathology in allergic asthma." (PMID 30782202, 2019). "IL-13, -4, and -5 are expressed abnormally in the allergic asthma mouse model." (PMID 31581442, 2019). "Early studies on transgenic mice revealed the dominating role of IL-13 in allergic asthma." (PMID 31262043, 2019). "IL-4 and IL-13 are crucial to the development of TH2 cells and induction of IgE isotype switching from B cells, which are the major risk factor for the development of allergic asthma." (PMID 31275149, 2019). "In addition, IL-13 is a key cytokine in allergic asthma and smoking allergic asthmatics show increased OPN sputum levels." (PMID 31664154, 2019). "The Th2 cytokines, IL-4, IL-5, and IL-13, were increased in patients of allergic asthma." (PMID 29086354, 2018). "Currently, IL-13 is considered as a potential pathway for target treatment in allergic asthma." (PMID 30210646, 2018). "IL-13 is a cytokine belonging to the alpha-helix protein family that is mainly produced by activated Th2 cells, mast cells, and basophils and has been widely studied in the scenario of helminth parasite infections and allergic asthma." (PMID 29675435, 2018). "Besides having been shown to play a critical role in helminth parasite infections and allergic asthma, IL-13 has been now suggested to exert additional functions in the development of metabolic alterations such as insulin resistance and hyperglycemia." (PMID 29675435, 2018). "The characteristic features of allergic asthma, including airway hyperreactivity, histopathology, cytokines (IL-4, IL-5, IL-13, IL-17, and INF-γ), and CD4+CD25+Foxp3+Treg cells in bronchoalveolar lavage fluid (BALF), and downstream proteins of mTORC1/2 signaling were examined." (PMID 29234390, 2017). "Another very important function of IL‐13 in allergic asthma is isotype switching to IgE by B cells." (PMID 27957328, 2016). "While IL-4 and IL-5 promote isotype switching of B cells to IgE producing cells and the infiltration of target tissues by eosinophils, IL-13 induces metaplasia of epithelial cells into goblet cells which is responsible for mucus hypersecretion in allergic asthma." (PMID 26999446, 2016). "For example, in the pathogenesis of allergic asthma, IL-4 and IL-13 play an important role in tandem, with IL-4 having a pivotal role in Th2 cell proliferation, cytokine production and IgE synthesis, whilst IL-13 plays a pivotal role in the effector phase of the disease." (PMID 26870894, 2016). "Doing so in vivo, macrophage E-cadherin could help to determine the outcome of typical Th2 cytokine-driven diseases like Taenia crassiceps helminth infection and allergic asthma, during which E-cadherin-expressing M(IL-4/IL-13) macrophages are present." (PMID 26226941, 2015).
allergic asthma (continued). "Eosinophils and mast cells may also be a source of IL-4 and IL-13, and in this study and earlier investigations these cells have been shown to be a key feature of the inflammation seen in the sheep model of allergic asthma." (PMID 26362930, 2015). "Many of the processes involved in allergic asthma can be directed to IL-13." (PMID 25849971, 2015). "IL-13 also plays important role in allergic asthma, such as eosinophilic lung infiltration and mucus hypersecretion, which could be observed in our allergic mice." (PMID 25890178, 2015). "Also in human allergic asthma, IL-13-producing CD8+ T-cells isolated from the lung are increased and associated with airway obstruction." (PMID 26137541, 2015). "Moreover, also in human allergic asthma, IL-13 producing CD8+ T-cells isolated from the lung are increased and associated with airway obstruction." (PMID 25803478, 2015). "IL-4 and IL-13 play a critical yet poorly understood role in orchestrating the recruitment and activation of effector cells of the asthmatic response and driving the pathophysiology of allergic asthma." (PMID 26362930, 2015). "Moreover, IL-13 is known to induce goblet cell proliferation and is a characteristic feature of allergic asthma." (PMID 25326908, 2014). "Moreover, CD34+ cells producing IL-5 and IL-13 are detected in the sputum of individuals with allergic asthma." (PMID 24822215, 2014). "LIGHT induces asthmatic cytokine IL-13 and fibrogenic cytokine transforming growth factor-β release from allergic asthma-related eosinophils expressing HVEM and alveolar macrophages expressing LTβR, respectively, thereby playing crucial roles in asthmatic airway remodeling." (PMID 24782592, 2014). "Moreover, Th2 cytokines such as IL-4, Il-5 and IL-13 are crucial for the pathogenesis of allergic asthma." (PMID 24671176, 2014). "This cytokine is not borrowed from the donor's plasma (as the detection level in normal plasma is under the minimum level of detection of IL-13 with our method [0 pg/ml]), and as shown here, IL-13 can be elicited upon appropriate in vitro stimulation (as described in an allergic asthma context)." (PMID 24830754, 2014). "IL-4 and IL-13 are two central Th2 effector cytokines upregulated in OVA-induced allergic asthma." (PMID 25058417, 2014). "Allergic asthma is characterized by overproduction of IL-4, IL-13 and high level of serum IgE." (PMID 24681543, 2014). "There is growing evidence supporting the role of IL-13 in allergic asthma." (PMID 24349268, 2013). "Moreover, we previously demonstrated that IL-13 levels are negatively correlated with the outcome of lung function in children with allergic asthma." (PMID 23300949, 2013). "There is overwhelming evidence linking IL-4 and IL-13 signaling to allergic asthma responses." (PMID 23940740, 2013). "Furthermore, IL-9 and IL-13 have recently been found to be involved in the pathogenesis of allergic asthma." (PMID 22855687, 2012). "Furthermore, activation of JAK-STAT and MAPK pathways by allergen-induced increase in IL-13 in allergic asthma has been demonstrated in goblet cell metaplasia." (PMID 21203431, 2010). "The current consensus as to the etiology of allergic asthma defines it is an aberrant T-helper-2 (Th2) type response to environmental allergens characterized by overproduction of IL-4, IL-5, and IL-13 which are critical in maintaining an ongoing IgE-mediated, eosinophilic inflammation." (PMID 20573261, 2010). "IL-4, together with IL-13, is required for Th2-cell development and is intimately involved in the regulation of immunoglobulin E (IgE) production by sensitized allergen-specific B cells, which is a fundamental mechanism in the pathogenesis of allergic asthma." (PMID 20671916, 2010). "In addition, both IL-4 and IL-13 genes have been reported to be increased 18 h after allergen exposure in patients with allergic asthma." (PMID 16551361, 2006).
allergic asthma (continued). "The data supports the hypothesis that gene modulation by IL-13 in ASM may be essential for the events leading to the development of allergic asthma." (PMID 15661077, 2005). "Additional studies are clearly needed to define the transcriptional regulation of the different "pro-asthmatic" genes by IL-13, which may lead to novel therapeutic approaches for the treatment of allergic asthma." (PMID 15661077, 2005). "Additionally, in the pandemic context, another study observed that bronchial epithelial cells in children with allergic asthma replicated to a lesser extent compared to healthy children, and treatment with IL-13 reduced viral replication in the allergic asthma group." (PMID 40564746, 2025). "Similarly, nanobodies that target the TH2 pathway (e.g., cytokines such as IL-5 and IL-13) could be delivered to the lungs to treat allergic asthma." (PMID 39062843, 2024). "Our results imply that dual IL-4/IL-13 vaccination may represent a cost-effective, long-term therapeutic strategy for the treatment of allergic asthma as demonstrated in mouse models, although additional studies are warranted to assess its safety and feasibility." (PMID 33976140, 2021). "On the other hand, it is noteworthy that published evidence clearly supports the proposition that overproduction of IL-4 and IL-13 may be responsible for the features of allergic asthma that are exacerbated in the offspring born to HFD-fed mice after challenge with OVA." (PMID 31805682, 2019). "One explanation is that IL-31 is one of these Th2-type cytokines that induce inflammation-related cytokines, such as IL-4, IL-5 and IL-13, which form the complex network of cytokines that governs the development allergic asthma and so that role of IL-31 may be covered by other stronger cytokines." (PMID 30647024, 2019). "However, IL-13 has been shown to be a more relevant mediator of allergic asthma." (PMID 30500834, 2018). "In the computational model, it was found that eosinophil-derived IL-13 could not sustain an allergic asthma response in the absence of T cell (or other cell type)-derived IL-13, but that IL-13 production by eosinophils was integral to the development of allergic asthma." (PMID 25426119, 2014). "Once activated, for example by IL-33 or IL-22, ILC2 secrete IL-5 and IL-13, contributing to AHR and airway inflammation in OVA-induced allergic asthma." (PMID 40095032, 2025). "IL-4 and IL-13 via IL4Rα signaling have been known to drive MCM in 10-day-old Tg+ mice and mice models of allergic asthma." (PMID 40406132, 2025). "GATA3 has previously been shown to have strong links to allergic asthma and the promotion of Th2 differentiation and the resulting release of cytokines regulating ASM contractility, including IL-13 and IL-5." (PMID 40131902, 2025). "Considering the restrictions of prevailing therapies, we have identified the novel feature of DMF in combating allergic asthma by reducing the production of pro-inflammatory cytokines, i.e., IL4, IL13, and IL17, in the bronchoalveolar tissue." (PMID 38711519, 2024). "In an allergic asthma model, IRF7 mediated the activation and function of ILC2s cells through BCL11B, increasing the expression of IL-5 and IL-13, which in turn promoted allergic respiratory inflammation and allergic asthma." (PMID 37251373, 2023). "BM-MSCs preconditioned with EPA decreased BALF inflammatory cell counts, levels of TH2 cytokines (IL-4 and IL-13), lung fibrosis, and the presence of mucus-producing cells, and improved lung function in experimental HDM-induced allergic asthma." (PMID 37007034, 2023). "In the allergic asthma, probiotics attenuate the influx of eosinophils to the airway and reduce the levels of MCP-1, and IL-13 level." (PMID 35296330, 2022). "Morin treatment downregulated the expression of BLT2, NF-κB, and Th2-cytokine (IL-1β, IL-4, IL-6, IL-13, and TNF-α) in the lungs of an allergic asthma rat model." (PMID 33917985, 2021).
allergic asthma (continued). "Allergic asthma is mediated by TH2 cells and type two innate lymphoid cells (ILC2) for production of inflammatory cytokines IL-5 and IL-13." (PMID 34366865, 2021). "To further reveal the relationship between m6A patterns and allergic asthma, we investigated the correlation between m6A patterns and thymic stromal lymphopoietin (TSLP), interleukin (IL)-33, IL-4, IL-5, and IL-13." (PMID 33763115, 2021). "In murine allergic asthma, CHI3L3 is highly expressed, correlated to levels of IL-4 and IL-13, binds to carbohydrates e.g. heparin/heparan sulfate proteoglycan; which are major contributors of pulmonary fibrosis (by stimulating TGF-β signaling in fibroblasts)." (PMID 32024540, 2020). "Characteristic of allergic asthma, CD4+Th2 lymphocytes secrete Th2 cytokines, interleukin (IL)-4, IL-13, and IL-5 that mediate the inflammatory immune response." (PMID 32477356, 2020). "In our results, IL-13 and IL-25 protein in the lung were upregulated by inhaled as compared to intranasal OVA challenge in OVA-induced allergic asthma." (PMID 31823765, 2019). "In addition, SG treatment could alleviate allergic asthma by reducing the inflammatory cells in bronchoalveolar lavage (BAL) fluid and by decreasing inflammatory factors, including IL-4, IL-5, IL-13, eotaxin, and IgE, which are linked with the decreased expression of iNOS and COX-2." (PMID 31572487, 2019). "Allergic asthma is an inflammatory airway disorder mediated by TH2 cells, which produce various effector cytokines (IL-4, IL-5, and IL-13)." (PMID 29696026, 2018). "In people with allergic asthma, RV-activated ST2+ innate lymphoid cells (ST2+ILC) were the predominant source of IL-33 augmented IL-13 release." (PMID 30174671, 2018). "When outside pollen season, an obvious decline tendency of IL-13+ILC2s was found in patients with pollen-allergic asthma (6.94 ± 3.16% vs. 4.17 ± 1.98%, P < 0.05) and in those with HDM-allergic asthma (1.89 ± 0.70% vs. 1.44 ± 0.55%, P < 0.05), respectively." (PMID 29449864, 2018). "Overall, these findings indicate that iNKT cells promote allergic asthma inflammation and AHR principally through the secretion of IL-4 and IL-13." (PMID 30105031, 2018). "IL-13 acts directly on airway epithelial cells and smooth muscle cells and thereby induces AHR and mucus hyperproduction in allergic asthma." (PMID 26965110, 2016). "In animal models of allergic asthma, ILC2-derived IL-13 is an essential inducer of mucus hypersecretion and inflammation." (PMID 27547445, 2016). "We also evaluated serum IgE production and Th2 inflammatory molecules generated by CKA-induced allergic asthma to ensure that MMDT inhibited the secretion of IgE and BALF inflammatory cytokines IL-4, IL-5, and IL-13." (PMID 24723965, 2014). "We also evaluated serum IgE production and Th2 inflammatory molecules generated by OVA-induced allergic asthma to ensure that EA decreased the levels of IgE and BAL fluid inflammatory cytokines, IL-4, IL-5, and IL-13." (PMID 22649477, 2012). "Thus, IL-13-induced, ADAM17-mediated release of TGFα, and subsequent epithelial cell proliferation, could contribute to the epithelial hypertrophy, as well as other features, associated with airway remodeling in allergic asthma." (PMID 17620132, 2007). "Wnt10b deficiency mice of allergic asthma results in enhanced memory T cell activation, increased Th2 polarization as evidenced by elevated IL-4 and IL-13 concentrations, and recombinant Wnt10b increases the percentage of naïve CD4+T and CD8+T cells in vitro, thereby mitigating allergic asthma." (PMID 40433386, 2025). "It is important to acknowledge that the levels of IgE and the Th2 cytokines IL4 and IL13 were also elevated in RSV-infected females, suggesting that these mice could be more vulnerable to allergic asthma." (PMID 40143355, 2025). "In an allergic asthma mouse model, an increased ILC2 number could be observed, which leads to increased IL-5 and IL-13 and worsens allergic inflammation and airway hyperreactivity." (PMID 39861052, 2025).